CTLA4 (cytotoxic T-lymphocyte associated protein 4)
Diseases named in the same sentence as CTLA4 in open-access papers (continued):
Sharing a sentence is not in itself a finding about the gene and the disease.
metastatic carcinoma (29 papers, 2013 to 2025). A carcinoma which has spread from the original site of growth to another anatomic site. "Clinical evidence has shown that blockade of the PD-1/PD-L1 pathway and Cytotoxic T-Lymphocyte-Associated protein 4 (CTLA-4) leads to sustained anti-tumor responses, significantly altering treatment outcomes in advanced and metastatic cancers." (PMID 39538305, 2024). "Inhibitors of immune checkpoints (ICIs), such as the cytotoxic T-lymphocyte-associated protein 4 (CTLA-4), programmed cell death protein-1 (PD-1), and its ligand programmed death-ligand 1 (PD-L1), are increasingly used for the treatment of metastatic cancers." (PMID 34268127, 2021). "Immune checkpoint blockade with antibodies targeting cytotoxic T lymphocyte-associated protein 4 (CTLA-4) and programmed cell death protein-1 (PD-1) has shown durable responses in a significant portion of patients with metastatic cancer." (PMID 28348554, 2017). "Particularly, immune checkpoint blockade, for instance, cytotoxic T lymphocyte-associated protein 4 (CTLA-4) and programmed cell death protein 1 (PD-1) inhibitors achieve positive progress in treating some metastatic cancer types, although many are still under clinical trials." (PMID 36157222, 2022). "The emergence of immune checkpoint blockade (ICB) therapy that targets programmed cell death protein 1/programmed cell death ligand 1 (PD-1/PD-L1) or anti-cytotoxic T lymphocyte-associated antigen-4 (CTLA-4) has markedly revolutionized the therapeutic landscape of patients with metastatic cancers." (PMID 34732240, 2021). "Indeed, antibodies directed the immune checkpoints CTLA-4 (cytotoxic T lymphocyte-associated protein 4) and PD-1 (programmed cell death protein-1) were shown to prolong the survival of cancer patients suffering from metastatic cancers." (PMID 31191545, 2019). "Although ICIs targeting PD-1 and CTLA-4 have proven to be effective in treating locally advanced or metastatic carcinoma, a significant portion of patients fail to respond to the treatment or experience early recurrence." (PMID 39990209, 2025). "Collectively, these results highlighted HPK1 in NK cells as a candidate target for treating metastatic cancer and its cooperative therapeutic combination with anti‐PD‐1 and anti‐CTLA‐4 therapy." (PMID 38828677, 2024). "Immune checkpoint inhibitors (ICIs), including anti-cytotoxic T lymphocyte-associated protein 4 (anti-CTLA4) and anti-programmed death cell protein 1 (anti-PD-1), are increasingly prescribed in metastatic carcinoma therapy." (PMID 36685488, 2023). "Clinical indications of CTLA4 inhibitors, often in combination with PD-1/PD-L1 inhibitors, include several advanced or metastatic cancers." (PMID 36224560, 2022). "Immune checkpoint inhibitors (ICIs) targeting programmed cell death 1 (PD-1) and cytotoxic T-lymphocyte antigen-4 (CTLA-4) are widely used to treat advanced metastatic cancers." (PMID 33927311, 2021). "Cancer immunotherapy with checkpoint-blocking antibodies targeting Cytotoxic T lymphocyte-associated antigen-4 (CTLA-4) and PD-1/PD-L1 can cause a long-term sustained response in patients with metastatic cancer of a wide range of histologies." (PMID 34911954, 2021). "Immune checkpoint inhibitors (ICIs), primarily inhibitors of programmed cell death protein 1 (PD-1) or its ligand, programmed cell death ligand 1 (PD-L1), and cytotoxic T-lymphocyte-associated protein 4 (CTLA-4), are now a standard treatment for many types of advanced/metastatic cancer." (PMID 40677709, 2025). "This retrospective observational study enrolled patients with metastatic cancer who underwent anti-PD-1, anti-PD-L1, and/or anti-CTLA-4 treatment and developed endocrine irAE at the National University Cancer Institute, Singapore, between June 2015 and December 2020." (PMID 35681667, 2022). "In this work, we hypothesize that lymphatic delivery of anti-CTLA-4 will have greater anti-tumor responses than systemic delivery in a preclinical model of metastatic cancer." (PMID 31754400, 2019).
metastatic carcinoma (continued). "While anti-CTLA-4 has also been shown to modify the immune status of the tumor microenvironment 1, the intrinsic site of therapeutic action for anti-CTLA-4 in locally advanced metastatic cancers remains in the tumor draining LNs (TDLNs) where naïve T-cells are activated against tumor Ags." (PMID 31754400, 2019). "When combined with anti-cytotoxic T-lymphocyte-associated protein 4 (CTLA-4) antibody, it enabled approximately 84% of treated tumor-bearing mice to achieve long-term survival and 34% to develop tumor-specific immunity, offering a promising approach for metastatic cancer treatment." (PMID 40860139, 2025). "The clinical success of cancer immunotherapy targeting immune checkpoints (e.g., PD-1, CTLA-4) has ushered in a new era of cancer therapeutics aimed at promoting antitumor immunity in hopes of offering durable clinical responses for patients with advanced, metastatic cancer." (PMID 34885161, 2021).
asthma (28 papers, 2011 to 2025). "In accordance with this evidence, a high dose allergen-CTLA-4-encoding DNA vaccine was shown to suppress Th2 immune responses induced by allergens in a mouse model of asthma." (PMID 36865540, 2023). "A meta-analysis study detected +49A/G polymorphism in CTLA-4 as an important risk factor for asthma susceptibility, especially in Asian individuals, children, and atopic patients." (PMID 36865540, 2023). "Genetic variants drive the onset and development of asthma, including cytotoxic T-lymphocyte-associated protein 4 (CTLA4) and interleukin-10 (IL-10) which are involved in immune system regulation and inflammation." (PMID 34525985, 2021). "Some of these studies have demonstrated a significant association of CTLA-4 polymorphisms with atopy or asthma." (PMID 22844542, 2012). "A number of studies assessed the association of cytotoxic T-lymphocyte associated antigen 4 (CTLA-4) gene polymorphisms with asthma in different populations." (PMID 22844542, 2012). "This meta-analysis of 17 case-control studies including 6378 cases and 8674 controls systematically evaluated the association between +49 A/G, −318 C/T, −1147 C/T, CT60 A/G, −1722 C/T, and rs926169 polymorphisms in the CTLA-4 gene and asthma risk." (PMID 22844542, 2012). "We performed a meta-analysis to examine the association between CTLA-4 polymorphisms and asthma susceptibility." (PMID 22844542, 2012). "Based on these findings, it is likely that the mechanisms underlying the regulation of inflammatory responses in asthma by S. mansoni antigens involve IL-10, T-regulatory cells, and other mechanisms such as the expression of CTLA-4." (PMID 22934153, 2012). "Twelve case-control studies identified an association between CTLA-4 −318 C/T polymorphism and asthma risk." (PMID 22844542, 2012). "In conclusion, allergy is associated to a constitutive ICOS over-expression and inducible CTLA-4 under-expression with Th2/Treg imbalance, when a constitutive CTLA-4 under-expression and Th1/Treg disequilibrium appears as a hallmark of asthma." (PMID 21356099, 2011). "Additionally, GSEA demonstrated that increased CCL14 levels were mostly associated with pathways related to asthma, the CTLA4 pathway, the intestinal immune network for IgA formation, CAMs, and the PD-1 signaling pathway." (PMID 39030403, 2024). "Multiple polymorphism studies have investigated the association between CTLA-4 and asthma severity and AHR, providing evidence for involvement of these polymorphisms in controlling helper T cell- mediated responses and total serum IgE levels in patients with asthma." (PMID 36865540, 2023). "Additionally, stimulation of PBMCs with house dust mite extract resulted in decreased expression of CTLA-4 mRNA in high-risk children, suggesting a potential association between defective expression of CTLA-4 and development of asthma." (PMID 36865540, 2023). "Determination of the genetic effects of CTLA-4 polymorphisms on asthma and sensitivity analyses." (PMID 22844542, 2012). "This meta-analysis suggested that the +49 A/G polymorphism in CTLA-4 was a risk factor for asthma." (PMID 22844542, 2012). "Considering a single study may lack the power of providing a reliable conclusion, we performed a meta-analysis to investigate the relationship between CTLA-4 gene variants and asthma." (PMID 22844542, 2012). "Numerous studies demonstrated that treatment with various species of CTLA4Ig, a soluble CTLA4 immunoglobulin fusion protein molecule, had effects in several diseases, such as preventing contact hypersensitivity, acquired immune deficiency syndrome, psoriasis vulgaris and asthma." (PMID 25177863, 2014). "Numerous pathways, including those involved in asthma, the CTLA4 pathway, the intestinal immunological network for IgA production, CAMs, and the programmed death 1 (PD-1) signaling pathway, have been associated with elevated levels of CCL14." (PMID 39030403, 2024).
asthma (continued). "Elevated expression of PD-1 and CTLA-4 in activated Th2 cells upon allergen exposure was observed in a mouse model of asthma." (PMID 36865540, 2023). "In a study of children with recurrent wheezing with high- or low-risk factors for asthma, a reduced absolute number and percentage of CD4+CD25+CTLA-4+ T cells was shown compared to healthy children." (PMID 36865540, 2023). "It was unique to the present case that cytotoxic T lymphocyte antigen 4 (CTLA-4) in CD4+ Forkhead box P3 (Foxp3) + T cells were upregulated in the early phase before the development of asthma attacks." (PMID 35029177, 2022). "Cytotoxic T lymphocyte antigen 4 (CTLA-4) in CD4+ FOX3+ T cells was upregulated in the early phase before the development of asthma attacks." (PMID 35029177, 2022). "The role of CTLA4-Ig as an adjuvant has also been reported in other studies including a model of asthma." (PMID 30822308, 2019). "The multiple linear regression analysis showed that asthma (A + AR) was associated to lower ICOS and CTLA-4 expression and Treg cell proportions, but to higher IFN-γ+ T cells." (PMID 21356099, 2011). "In addition to genetic associations, increased plasma concentration of CTLA-4 protein and cell expression of TIM-3 have been proposed as biomarkers for asthma susceptibility and severity in different studies." (PMID 36865540, 2023). "MiR-155, a crucial immunoregulatory factor, can promote the proliferation of T cells and inhibit cytotoxic T lymphocyte-associated protein 4 (CTLA-4), and regulate the activation and differentiation of Th2 cells, thereby playing a role in the development of asthma." (PMID 36865391, 2023). "In addition, the percentage of CD4+ T cells expressing surface CTLA-4 inversely correlates with asthma severity, as determined by the ACT scores." (PMID 29507584, 2018). "CTLA-4 involvement has been reported in food allergy as well as the establishment of Th1 and Th2 balance, while PD-1 expression by Tregs was shown to play a major role in an animal model of antigen-induced asthma." (PMID 30475891, 2018). "Genetically engineered CTLA4 DCs were utilized in many studies, including asthma therapy." (PMID 25177863, 2014). "Additionally, polymorphisms in the PTPN22 (protein tyrosine phosphatase non-receptor 22) and CTLA-4 (cytotoxic T lymphocyte-associated antigen 4) genes have been strongly associated with asthma prevalence and morbidity." (PMID 40599789, 2025). "However, asthma severity was inversely correlated only with the frequency of CTLA-4+ CD4+ T cells." (PMID 29507584, 2018). "However, NPSR1 and CTLA4 can be genetic links between AR and asthma and associations of polymorphisms in NPSR1 with AR have not been reported previously." (PMID 23663310, 2013). "Cumulative evidence suggested that CTLA-4 may play an important role in the pathogenesis of asthma." (PMID 22844542, 2012). "The CD80/CD86-CD28 axis is a critical pathway for immuno-corrective therapy, and the cytotoxic T lymphocyte antigen 4 (CTLA4) is a promising immunosuppressor targeting the CD80/CD86-CD28 axis; however, its use for asthma therapy needs further optimization." (PMID 25177863, 2014). "Asthma is believed to have a strong genetic background, and hundreds of genes have been identified to be related with asthma, including GSTM1, IL10, CTLA-4, SPINK5, LTC4S, IL4R, and ADAM33." (PMID 24790987, 2014). "The relationship between MALAT1 and CTLA4 is not previously studied in cancer; however, its data in asthma showed that MALAT1 sponges miR-155 upregulating CTLA4." (PMID 36387279, 2022). "In conclusion, our meta-analysis suggested that the +49 A/G polymorphism in CTLA-4, but not the −318 C/T, −1147 C/T, CT60 A/G, −1722 C/T, or rs926169 polymorphisms, represented a risk factor for asthma." (PMID 22844542, 2012). "Our objective was to assess whether allergen-induced T cell activation differs from allergic rhinitis to allergic rhinitis with asthma, and explore the role of ICOS, CD28 and CTLA-4." (PMID 21356099, 2011).
asthma (continued). "A number of studies showed that administration of CTLA-4-Ig significantly ameliorated airway hyperresponsiveness (AHR), reduced the level of eosinophils in average bronchoalveolar lavage fluid and serum IgE, as well as cytokine production in murine asthma model." (PMID 22844542, 2012). "The results convincingly showed that asthma is no confounding factor for the SNPs in NPSR1 and CTLA4 in the Chinese population." (PMID 23663310, 2013). "Increases in CTLA-4 and TIM-3 expression in CD4+ T cells (not CD8+), as well as an increase in Th17 cells, may reflect asthma-related inflammation activity." (PMID 35029177, 2022). "Increases in CTLA-4 and TIM-3 expression not on CD8+ but CD4+ T cells, as well as an increase in Th17 cells, may reflect asthma-related inflammation activity." (PMID 35029177, 2022).
lung adenocarcinoma (28 papers, 2015 to 2025). A carcinoma that arises from the lung and is characterized by the presence of malignant glandular epithelial cells. "In these immune checkpoint analysis results, we discovered a hot immunotherapeutic molecule, cytotoxic T-lymphocyte-associated protein 4 (CTLA4), which may guide the treatment of CTLA4 antibodies such as ipilimumab in lung adenocarcinoma." (PMID 37643369, 2023). "This study aimed to identify CTLA-4-related long non-coding RNAs (lncRNAs) and assess their roles in lung adenocarcinoma (LUAD) development." (PMID 39143529, 2024). "To further explore the mechanism of predict model, we investigated the immune characteristics of the tumor microenvironment and PD‐1, PD‐L1, and CTLA‐4 expression in patients with lung adenocarcinoma." (PMID 35246970, 2022). "In lung adenocarcinoma, Lou et alfound that multiple immune checkpoints associating with increased regulatory T cells including PD-L1, PD-1, TIM-3, B7-H3, BTLA and CTLA-4 displayed EMT phenotype." (PMID 36467998, 2022). "Here, we investigated the potential role of miR-33a and demonstrated its potential value as prognostic marker by regulating PD-1/PD-L1 and CTLA4 expression in lung adenocarcinoma." (PMID 29176936, 2017). "Simultaneous quantification of the expression level of miR-33a and PD-1, PD-L1 and CTLA4 mRNAs with NanoString technology was performed in 88 lung adenocarcinoma specimens." (PMID 29176936, 2017). "Approximately 50–60% of the CD4+CD25+CD127− Treg cells expressed CTLA-4 in lung adenocarcinoma patients and the control groups." (PMID 26582240, 2015). "Immunotherapy, another critical field in lung adenocarcinoma treatment, has also gained approval for non-small cell lung cancer, including lung adenocarcinoma, with PD-1/PD-L1 inhibitors like nivolumab, pembrolizumab, atezolizumab, and CTLA-4 inhibitors like ipilimumab." (PMID 38167018, 2024). "This hypothesis is consistent with a report where a high level of immune infiltration induces EMT followed by up-regulation of immune checkpoints such as CTLA-4 and PD-L1 in lung adenocarcinomas." (PMID 36428693, 2022). "However, it has been recently shown that CTLA4 may play the tumour suppressor role across different cancer, including lung adenocarcinoma." (PMID 31877723, 2019). "In lung adenocarcinoma, YTHDF1 is significantly negatively correlated with PD-L1, PD-1, PD-L2, CTLA-4, TIGIT, VISTA, and TIM3." (PMID 36479088, 2022). "Finally, we found that COL11A1 is positively correlated with HAVCR2(TIM3), CD274 (PD-L1), CTLA4, and LAG3 in lung adenocarcinoma." (PMID 38649961, 2024). "Then, multivariate ROC showed that programmed cell death risk score (AUC:0.705) was more effective than PD-1 (AUC:0.453), PD-L1(AUC:0.497), CTLA4(AUC:0.417), TMB(AUC:0.506), LAG3(AUC:0.485), TIM-3(AUC:0.419), and MSI(AUC:0.475) in predicting the prognosis of lung adenocarcinoma." (PMID 36983658, 2023). "Thus, our results show that CD4+CD25+CD127− Treg cells from the smoking and nonsmoking groups and from lung adenocarcinoma patients did not mediate suppressor activity by IL-10 production; nevertheless, CTLA-4 may be involved in the suppressor function." (PMID 26582240, 2015). "In a lung adenocarcinoma TMA, protein expression of immune checkpoint molecules (A2A, BTLA, CTLA4, INOS, TIM3, and PDL1) did not correlate with MFS or overall survival." (PMID 30783512, 2019).